ESR2 (estrogen receptor 2)
Diseases named in the same sentence as ESR2 in open-access papers (continued):
Sharing a sentence is not in itself a finding about the gene and the disease.
prostate tumor (15 papers, 2007 to 2024). "The mRNA levels of PPFIBP2 and ESR2 are differentially expressed in prostate tumours and paired normal tissues." (PMID 26443449, 2015). "We analyzed TCGA gene expression profiles of 497 prostate tumor samples according to 43 genes involved in EMT and 3 hormone receptor genes (AR, ESR1, ESR2) as well as clinical characteristic of cancer patients." (PMID 29206234, 2017). "In the 4,490 prostate tumor biopsies, APUC-6 genes exhibited a robust correlation with one another, and all had strong positive correlations with ESR1, ESR2, and PGR (Spearman’s R 0.13–0.52), while the correlation with AR was relatively weak (Spearman’s R 0.06–0.20)." (PMID 39207857, 2024). "We also found that ESR2 was upregulated in prostate tumour tissues compared with normal prostate tissues in The Cancer Genome Atlas (TCGA) data (Pt-test=0.028)." (PMID 26443449, 2015). "However, the magnitude of ESR2 mRNA expression was not high, which should be confirmed via analysis of the expression levels of ESR2 protein in prostate tumour tissues." (PMID 26443449, 2015).
lymphoma (14 papers, 2015 to 2024). A malignant (clonal) proliferation of B- lymphocytes or T- lymphocytes which involves the lymph nodes, bone marrow and/or extranodal sites. "Though human lymph nodes express both ESR1 and ESR2, the predominantly expressed nuclear estrogen receptor in normal lymphocytes and lymphomas is ESR2." (PMID 35804870, 2022). "Furthermore, the data suggested an interplay between the lymphoma cells and the tumor microenvironment in response to the ESR2 agonist." (PMID 35804870, 2022). "Furthermore, the results suggested an interplay between the lymphoma cells and the tumor microenvironment in response to ESR2 activation." (PMID 35804870, 2022).
esophageal cancer (13 papers, 2009 to 2023). A primary or metastatic malignant neoplasm involving the esophagus. "The expression levels of ESR1 and ESR2 RNA (encoding ERα and ERβ protein, respectively) in esophageal cancer were not significantly different from those in the normal esophageal samples (p > 0.05)." (PMID 37762356, 2023). "The results showed that the RNA levels of ESR1 and ESR2 were not significantly different between esophageal cancer and normal esophagus, and were not correlated with the total survival time of the tumor patients." (PMID 37762356, 2023).
asthma (12 papers, 2012 to 2026). "ESR2 and its product, estrogen receptor β, have been suggested as potential targets for asthma treatment." (PMID 34566951, 2021). "HTR2C, CYP1B1, CYP19A1, ESR1, ESR2, PDR, and AR are found to be interrelated to hormonal disorders; ABCC1, NQO1, TIMP1, ADRB2, and ALOX5 are associated with asthma." (PMID 29861771, 2018).
liver fibrosis (12 papers, 2018 to 2025). "In addition, among all common targets for RGGs and liver fibrosis, ESR1, ESR2, AR, ACHE, CYP19A1, and AKR1B1 have a high degree of interaction with other targets and some active compounds." (PMID 35115923, 2021).
Alzheimer disease (11 papers, 2009 to 2026). A progressive, neurodegenerative disease characterized by loss of function and death of nerve cells in several areas of the brain leading to loss of cognitive function such as memory and language. "The role of ESR2 in the development and progression of Alzheimer ’s disease (AD) has been well accepted." (PMID 32751183, 2020).
Insulin resistance (11 papers, 2015 to 2025). Increased resistance towards insulin, that is, diminished effectiveness of insulin in reducing blood glucose levels. "High adipose tissue ESR2 expression levels are associated with metabolic perturbations such as insulin resistance." (PMID 35856485, 2022). "Transcripts with loss of function, such as Apom, Mc4r and Esr2 are strongly associated with glucose intolerance and/or insulin resistance." (PMID 32651395, 2020). "In addition, hyperglycaemia and insulin resistance markers were negatively associated with ESR2 expression." (PMID 35856485, 2022). "Taken together, high ARO and altered ESR1:ESR2 balance in SAT in obese men may contribute to insulin resistance and T2D development." (PMID 39833659, 2025). "The role of ESR2 on adipocyte glucose and lipid metabolism is more complex, with some studies suggesting a role in insulin resistance, whereas others demonstrate a protective role against adiposity and insulin resistance." (PMID 39833659, 2025).
metastatic disease (10 papers, 2010 to 2024). "When revisiting the metastatic tumors stratified by APUC-6 levels, we found that tumors with high APUC-6 expression had increased expression of ESR1, ESR2, and PGR, but reduced expression of AR." (PMID 39207857, 2024).
adenoma (9 papers, 2014 to 2025). A neoplasm arising from the epithelium. "FZD9-/- female mice exhibited higher mRNA levels of ESR1 and ESR2 in both whole lung and adenomas when compared to all male mouse groups and to wild-type female groups." (PMID 35924166, 2022). "Here, ESR2 was elevated significantly in male FZD9-/- adenomas and non-significantly in female FZD9-/- adenomas." (PMID 35924166, 2022).
cognitive decline (9 papers, 2013 to 2026). "Furthermore, single-nucleotide polymorphisms (SNPs) of the ERβ-encoding gene (ESR2) have also been associated with cognitive decline and an increased risk of AD in women, demonstrating the involvement of this receptor in the pathological mechanisms of the disease." (PMID 37509151, 2023). "Furthermore, the relative ESR2/ESR1 expression ratio is increasingly appreciated as important in memory performance and cognitive decline with respect to age." (PMID 30635056, 2019).
heart failure (9 papers, 2005 to 2024). Inability of the heart to pump blood at an adequate rate to meet tissue metabolic requirements. "One study showed that exogenous therapy with E2 rescues pre-existing advanced heart failure (HF) in mice mainly by regulating ESR2 expression." (PMID 35992774, 2022).
ischemia (9 papers, 2006 to 2023). A hypoperfusion of the BLOOD through an organ or tissue caused by a PATHOLOGIC CONSTRICTION or obstruction of its BLOOD VESSELS, or an absence of BLOOD CIRCULATION. "In primary neocortical cell cultures subjected to 18 h of ischemia followed by a 6 h reoxygenation period, we observed a significant increase in Esr2 and Gper1 mRNA expression (2.33- and 4.24-fold, respectively)." (PMID 37129835, 2023). "Moreover, ospemifene (10 μM) normalized the levels of ESR2 diminished in response to both hypoxia and ischemia as well as normalized the GPER1 level elevated in response to ischemia." (PMID 37129835, 2023).
mesothelioma (9 papers, 2014 to 2024). A usually malignant and aggressive neoplasm of the mesothelium which is often associated with exposure to asbestos. "When it came to male patients, high ESR2 expression levels in HNSC, LUAD, and PAAD and low ESR2 expression levels in KIRP, LAML, mesothelioma (MESO), STAD, and THCA were attributed to longer OS." (PMID 39201394, 2024).
schizophrenia (9 papers, 2012 to 2026). A major psychotic disorder characterized by abnormalities in the perception or expression of reality. "The estrogen receptor 2 (ESR2), which is among few genes with a link to schizophrenia, was found to have switched from a strong positive correlation for AI (sources) in mouse to a strong negative correlation in humans." (PMID 38877144, 2024). "Given the role of estrogen in the treatment of schizophrenia, we also examined sex hormone-related expression (AR, ESR1, ESR2, and PGR) in the brain." (PMID 38730231, 2024). "Here, we did not observe any sex-specific or sex-specific schizophrenia DEGs for sex hormone expression (AR [androgen receptor], ESR1 [estrogen receptor 1], ESR2 [estrogen receptor 2], and PGR [progesterone receptor]) across the brain." (PMID 38730231, 2024).
adenomyosis (8 papers, 2012 to 2025). The growth of endometrial tissue inside the muscular wall of the uterine corpus. "The increased expression of ESR1 and ESR2 in PP adenomyosis lesions, although based on limited data, may indicate a heightened sensitivity to E2 in these tissues." (PMID 39935764, 2025). "In adenomyosis, decreased expression of ESR1 and increased expression of ESR2 can be observed, attributable to the methylation-mediated suppression of ESR2 in normal endometrial tissue." (PMID 41278208, 2025). "All estradiol receptor (ESR1, ESR2, GPER) expression levels were significantly higher in adenomyosis than in normal myometrium." (PMID 35956024, 2022).
coronary artery disease (8 papers, 2010 to 2025). "In aorta, we identified perturbations in a number of TFs involved in circadian clock regulation (CRY1, CRY2, PER2), vascular inflammation (PPARG, NR3C1), and those linked in coronary artery disease, including the estrogen receptor, ESR2." (PMID 39896461, 2025).
dyslipidemia (8 papers, 2017 to 2025). "The ESR1 and ESR2 genotypes are associated with insulin sensitivity and metabolic syndrome in Japanese and Chinese women." (PMID 33777160, 2021). "The study indicated that LETZ-treated mice displayed symptoms of PCOS, such as dyslipidemia, hyperinsulinemia, elevated testosterone, increases in inflammatory markers and malonaldehyde, and a decline in antioxidants (Ar, lhr, fshr, and esr2) in the ovaries." (PMID 36979879, 2023).
liver cancer (8 papers, 2016 to 2024). An epithelial or non-epithelial malignant neoplasm that arises from the liver. "Liver cancer-resistant Esr1 heterozygous, Esr2 heterozygous, and Esr2 KO females were found to have a uterus weight similar to that seen in intact B6 animals and estrogen-treated ovariectomized B6 mice." (PMID 34068249, 2021). "The relatively small change in the gene expression profile of ESR2 (p-value < 0.45) between old normal liver cells and old liver cancer cells implicates that the gene expression change of ESR2 could be necessary but not sufficient for hepatocarcinogenesis." (PMID 26897165, 2016). "The gene expression profile of ESR2 showed the change (p-value < 0.091) between young and old normal liver cells, and the change (p-value < 0.063) between young normal liver cells and young liver cancer cells." (PMID 26897165, 2016).
myocardial infarction (8 papers, 2005 to 2025). Gross necrosis of the myocardium, as a result of interruption of the blood supply to the area, as in coronary thrombosis. "Further, a number of candidate gene studies have identified associations with increased risk of CAD or myocardial infarction (MI) in individuals with deleterious variants in the estrogen receptor 1 (ESR1 or ERα,) or 2 genes (ESR2 or ERβ) causing dysfunctional or null activity." (PMID 40182431, 2025).
diffuse large B-cell lymphoma (7 papers, 2021 to 2024). "The expression of ESR2 RNA was elevated in diffuse large B-cell lymphoma (DLBC)." (PMID 38666956, 2024). "ESR2 mRNA was observed to be highly expressed only in the lymphoid neoplasm diffuse large B-cell lymphoma (DLBCL) samples, whereas a low expression of ESR2 mRNA was found in adrenocortical carcinoma (ACC), OV, and TGCT samples." (PMID 34322374, 2021). "In the case of patients with lymphoid neoplasm diffuse large B-cell lymphoma (DLBC) (p-value = 0.001) and thymoma (THYM) (p-value = 0.013), a high ESR2 expression level was a positive prognostic factor." (PMID 39201394, 2024).
hypospadias (7 papers, 2019 to 2025). Hypospadias is the displacement of the urethral meatus on the ventrum of the penis. "ESR1 SNPs and haplotypes influence the risk of hypospadias in nonHispanic white and Hispanic population, while variants in ESR2 are associated with hypospadias in the Swedish cohort." (PMID 31856834, 2019).
lupus (7 papers, 2016 to 2024). "Further evidence that ESR1, not ESR2, produces the lupus phenotype can be found in male mice lacking functioning ESR1." (PMID 38835801, 2024).
pancreatic adenocarcinoma (7 papers, 2018 to 2025). "In pancreatic adenocarcinoma (PAAD), a significant positive correlation has been observed between the levels of estrogen receptors ESR1 and ESR2 and TLS scores in the TME." (PMID 40303343, 2025).
Crohn disease (6 papers, 2016 to 2025). A gastrointestinal disorder characterized by chronic inflammation involving all layers of the intestinal wall, noncaseating granulomas affecting the intestinal wall and regional lymph nodes, and transmural fibrosis. "Additionally, studies on IBD presented lower ESR2 expression levels in colonic mucosa of Crohn’s disease (CD) and ulcerative colitis (UC) patients compare with controls." (PMID 29383180, 2017).
Hodgkins lymphoma (6 papers, 2018 to 2025). A heterogeneous group of malignant lymphoid neoplasms of B-cell origin characterized histologically by the presence of Hodgkin and Reed-Sternberg (HRS) cells in the vast majority of cases. "ESR2 expression levels were highest in DLBCL and mantle cell lymphoma, followed by Burkitt lymphoma and Hodgkin lymphoma." (PMID 35256592, 2022).
idiopathic scoliosis (6 papers, 2016 to 2023). A scoliosis with no known cause. "A recent cross-sectional study revealed that some ESR1 and ESR2 variants were associated with the occurrence risk of idiopathic scoliosis." (PMID 34064195, 2021). "We have already published on ESR1 and ESR2 gene polymorphisms association with idiopathic scoliosis occurrence and severity." (PMID 27045366, 2016). "Moreover, many promising polymorphisms within different genes (including ESR1, ESR2) have been identified for the occurrence and curve progression of idiopathic scoliosis." (PMID 35627124, 2022). "Little is known about ESR2 genetic alterations concerning skeletal muscle tissue function, which is impaired in idiopathic scoliosis." (PMID 35627124, 2022). "In conclusion, the ESR1 and ESR2 presence was confirmed in skeletal paravertebral muscles of patients with idiopathic scoliosis." (PMID 35627124, 2022). "The study aimed to detect the presence and assess the expression levels of the estrogen receptors type 1 (ESR1) and type 2 (ESR2) within paravertebral skeletal muscles of female patients with idiopathic scoliosis (IS) in relation to phenotype parameters." (PMID 35627124, 2022). "Our previous studies focused on the ESR2 gene polymorphism in patients with idiopathic scoliosis, as well as on methylation of both ESR1 and ESR2 genes." (PMID 35627124, 2022). "Using the reverse transcription followed by polymerase chain reaction, the western blot, and immunohistochemistry techniques, the estrogen receptors ESR1 and ESR2 presence were confirmed in the muscular cells of the paraspinal skeletal muscles in a cohort of children with idiopathic scoliosis." (PMID 35627124, 2022). "However, there has yet to be an assessment of DNA methylation at ESR2 regulatory regions in the deep paravertebral muscles of patients with idiopathic scoliosis." (PMID 33339862, 2020). "In conclusion, our results demonstrate that the methylation pattern of CpG sites in the regulatory regions of the ESR2 gene in the deep paravertebral muscle tissue is associated with the occurrence but not with the severity of idiopathic scoliosis." (PMID 33339862, 2020). "Our findings demonstrate that DNA methylation at the ESR2 promoter in deep paravertebral muscle tissue is associated with the occurrence but not with the severity of idiopathic scoliosis." (PMID 33339862, 2020).
leiomyoma (6 papers, 2017 to 2023). A well-circumscribed benign smooth muscle neoplasm characterized by the presence of spindle cells with cigar-shaped nuclei, interlacing fascicles, and a whorled pattern. "However, the genetic contribution of ESR2 to leiomyoma risk needs to be further explored." (PMID 31423418, 2019). "Similar results were obtained from the GO enrichment analysis of DEGs in endothelial cells between pseudocapsule and leiomyoma and ESR2 was mainly expressed in endothelial cells of leiomyoma in P2-SC." (PMID 37215998, 2023). "In P2-SC, endothelial cells included clusters 8 and 12, and ESR2 was significantly up-regulated in endothelial cells of leiomyoma compared to pseudocapsule." (PMID 37215998, 2023). "We found that the highest expression of ESR2 was in endothelial cells of leiomyoma, indicating that ERβ might play an important role in the angiogenesis of uterine leiomyoma since uterine leiomyoma is an estrogen dependent disease." (PMID 37215998, 2023). "The chromosomal location of ESR2 gene has been frequently rearranged in uterine leiomyomata and other benign tumors which could play a major role in the etiology of leiomyomas." (PMID 31423418, 2019). "ESR1, estrogen receptor 2 (ESR2) and PGR were significantly up-regulated in endothelial cells of leiomyoma compared to pseudocapsule." (PMID 37215998, 2023).
mood disorder (6 papers, 2011 to 2025). A cognitive disorder a disturbance in which the person's mood is hypothesized to be the main underlying feature. "Dysregulation of LMX1B increases pain sensitivity and mood disorder risk, while ESR2 affects pain thresholds and mood via estrogen signaling, underscoring their role in the complex interplay of pain and mood regulation." (PMID 40313396, 2025). "The present findings suggest that differential manipulation of Esr1 and Esr2 in males and females might have potential applications for the treatment of mood disorders." (PMID 30863326, 2019).
type 2 diabetes (6 papers, 2020 to 2025). "E2 acts through estrogen receptors ESR1 and ESR2, and they potentially affect development of type 2 diabetes (T2D)." (PMID 39833659, 2025).
acute myeloid leukemia (5 papers, 2013 to 2024). Acute myeloid leukemia (AML) is a group of neoplasms arising from precursor cells committed to the myeloid cell-line differentiation. "Further, a meta-analysis of gene signatures in acute myeloid leukemia did not establish a direct link between ESR2 expression and patient survival." (PMID 39201394, 2024). "In contrast, ESR2 expression levels were not higher in other malignancies such as acute myeloblastic leukemia (AML) or BC compared to their normal counterparts." (PMID 35256592, 2022).
Autoimmunity (5 papers, 2010 to 2023). The occurrence of an immune reaction against the organism's own cells or tissues. "Thus, the systemic deregulation of ESR1 and ESR2 genes found in CP/CPPS could indicate a dendritic cell mediated autoimmunity for CP/CPPS." (PMID 29731970, 2018).
B-cell lymphoma (5 papers, 2019 to 2025). "Next, we determined ESR2 mRNA expression by NanoString in a cell line panel consisting of human B-cell lymphoma (n = 39), human T-cell lymphoma (n = 4), multiple myeloma (n = 5), AML (N = 5) and as a positive control the human BC cell line MCF7." (PMID 35256592, 2022).
hyperlipidemia (5 papers, 2018 to 2024). "The estrogen signaling pathway was regulated by CA binding to HSP90AA1, MMP2, RARA, PRKACA, ESR1, MMP9, and ESR2 in this present research, which underlies the improvements observed in hyperlipidemia and thrombosis." (PMID 38398534, 2024).
migraine (5 papers, 2012 to 2024). "Significant interactions were observed for CYP19A1 rs10046 with ESR2 rs1271572, ESR1 rs2234693 and ESR1 rs9340799 polymorphisms conferring risk for migraine susceptibility." (PMID 22511967, 2012). "According to one research, estrogen receptor 1 (ESR1) and estrogen receptor 2 (ESR2) may contribute to the hereditary basis of migraine." (PMID 37123778, 2023). "Based on these findings, we suggest CYP19A1 polymorphisms to be the major contributing factor in migraine susceptibility rather than ESR1and ESR2 polymorphisms as shown by interactions of genotypes and haplotypes." (PMID 22511967, 2012).
autoimmune disease (4 papers, 2010 to 2023). A disorder resulting from loss of function or tissue destruction of an organ or multiple organs, arising from humoral or cellular immune responses of the individual to their own tissue constituents. "Except ESR2, the majority of these proteins have not been previously reported to associate with any autoimmune diseases." (PMID 33545363, 2021).